KRT13 (keratin 13)
Diseases named in the same sentence as KRT13 in open-access papers (continued):
Sharing a sentence is not in itself a finding about the gene and the disease.
tumor (46 papers, 2009 to 2026). "Deregulation of KRT4 and KRT13 genes is associated with impaired epithelial differentiation and organization during tumor progression, and they are normally expressed in the oral cavity." (PMID 39140365, 2024). "Taken together, these results indicate that KRT13 is prominent in tumor foci associated with aggressive disease." (PMID 27711225, 2016). "For example, PIM1 is an ER regulated proto-oncogene that has been shown to play a role in BCa cell proliferation, migration and metastasis and is associated with high grade tumours; KRT13 has been associated with BCa cell growth and metastasis and LOXL4 is an established promoter of cell invasion." (PMID 25488809, 2015). "The suprabasal markers KRT4 and KRT13, commonly expressed in skin homoeostasis, were also differentially upregulated at RNA level in the tumours derived from the Ivl:BRAFV600E model." (PMID 41507151, 2026). "In pt #003, KRT10 and KRT13 were detected within the central cells of the organoid, consistent with expression in the matched patient tumor tissue section." (PMID 40624315, 2025). "Both tumor tissues showed strong reactivity with the KRT13 antibody, confirming their squamous epithelial origin." (PMID 39138148, 2024). "The group I contain only two genes KRT4 and KRT13 which are under expressed in tumor data and over expressed in normal data." (PMID 39140365, 2024). "As KRT13 was specifically expressed in tumor tissues, we selected the cluster 3 (including 1,506 spots) with the highest KRT13 log2FC in malignant cells." (PMID 37124494, 2023). "The results revealed that KRT13+FABP5+ malignant cell subpopulation had keratinization characteristics in the tumor tissue." (PMID 37124494, 2023). "By controlling the expression of c-myc, the oncogene KRT13 encourages tumor cell proliferation and invasion." (PMID 37064125, 2023). "We noted that some tumour cells, for example, tumour‐03, carried early differentiation marker KRT13, which was validated in HIN tissues." (PMID 35608199, 2022). "Differential analysis showed that proliferation and antigen presentation genes, such as STMN1 and HLA‐DRA, were slightly up‐regulated in tumour cells, whereas differentiation molecules, such as KRT13, HOPX and CD24, were highly expressed in normal cells." (PMID 35608199, 2022). "Similar correlations between KRT13 levels and xenograft tumor formation were observed with HCC1954 cells." (PMID 35078507, 2022). "In our study, KRT13-overexpression led to decreased DSP and PG, reducing tumor suppressor functions in MCF7-KRT13 cells." (PMID 35078507, 2022). "Intensity analysis shows that KRT13 levels are lower in tumor tissue compared to healthy prostate, in agreement with the MS and ELISA data." (PMID 35267445, 2022). "Several epithelial markers were elevated in RE, Keratin 13, Keratin 20, and Gastrokine-1, relative to other groups, while neoplasia markers desmin and vimentin were elevated in BE and EAC compared to control." (PMID 32650561, 2020). "Immunostaining of a prostate tissue microarray revealed KRT13+ tumor foci in approximately 9% of cases, and this subset displayed significantly shorter time to recurrence (p = 0.031), metastases (p = 0.032), and decreased overall survival (p = 0.004)." (PMID 27711225, 2016). "If cancers become more differentiated and less aggressive, KRT13 expression should be lost in tumor cells." (PMID 27711225, 2016). "Perhaps maintanence of KRT13 expression in tumors is dependent upon the degree of differentiation that occurs during tumor progression." (PMID 27711225, 2016). "In the ARCaP model, KRT13 overexpression increased tumor bone and brain metastases from 12.5 to 80% and 0 to 20%, respectively." (PMID 27835867, 2016). "Diagnostic prostate needle biopsies (PNBX) from untreated patients with concurrent bone metastases (clinical stage M1) displayed KRT13+ tumor foci, as did bone metastatic foci." (PMID 27711225, 2016).
tumor (continued). "One observation related to KRT13 expression in cancer specimens is the often discordant relationship between its expression in HGPIN and cancer, that is, KRT13 expression in HGPIN is significantly more prevalent than it is in tumor foci." (PMID 27711225, 2016). "We confirmed the organoids’ tumor identity using immunostaining against KRT13." (PMID 39138148, 2024). "T-C6 was concentrated in a small area in the tumor section, with the overexpression of KRT13 and FABP5 (encoding a fatty acid binding protein found in epidermal cells), which suggested that these spots primarily represented the tumor cells derived from the pancreatic ductal epithelium." (PMID 37124494, 2023). "In our study, KRT13-induced stemness, behavioral changes, and xenograft tumor growth and metastasis could be attributed to c-Myc dysregulation." (PMID 35078507, 2022). "Using data retrieved from our previous study, we demonstrated that the gene expression level of KRT13 was significantly down-regulated in OSCCs compared to their corresponding non-tumor epithelia, while the expression levels of KRT17, MKI67, and LAMC2 in OSCCs were significantly upregulated." (PMID 35524231, 2022). "In addition, the highly phosphorylation (e.g., HSPB1 S82, KRT14, KRT13 S427, etc.)were both detected in tumor tissues and their paired normal tissues in EESCC." (PMID 35397555, 2022). "Importantly, the knockdown of KRT13 by siRNA in primary cells from one patient specimen significantly decreased the tumor spheroid formation, likely by inhibiting cancer stem-like cell self-renewal." (PMID 34360875, 2021). "Future studies that evaluate the effect of direct transformation of benign KRT13+ prostate epithelial cells may reveal the importance of KRT13 expression in tumor evolution." (PMID 27711225, 2016). "On the other hand, if tumor cells remain in a ‘stem-like’ state, characterized by KRT13 expression, they could be more prone to metastasis or resistance to ADT." (PMID 27711225, 2016). "Of note, several of these genes (such as Grem1, Hmga1, and Krt13) are specifically expressed by cancer cells, but not by other cell populations, indicating that these genes are potential markers associated with tumor metastasis." (PMID 37190324, 2023). "However, in tumor tissue, only KRT13 could identify T-C6 from the other seven clusters, suggesting that KRT13 is a specific marker of T-C6." (PMID 37124494, 2023). "UMAP clustering defined five cell clusters (cluster 0-4) of cancer cells in the tumor spheroids, with cluster 2 distinctly separated from the other cell types and enriched in stem cell markers including newly identified stemness keratin gene KRT13 (purple dots)." (PMID 34360875, 2021). "All five clusters of tumor epithelial cells were indeed observed in AM samples by using marker genes (HLA-B for IR, SFRP1 for BR, KRT13 for ED, ODAM for TD, LAMC2 for TD, and KI67 for CC)." (PMID 38424060, 2024). "In the case of other types of KRT (KRT13, KRT14, KRT24) in HNSCC, OSCC, and neoplastic oral mucosa, decreased protein levels were observed in the tumor sample compared to the margin/healthy tissue, which is consistent with our results." (PMID 39000463, 2024). "We used Oncomine datasets (Ye Head‐Neck, and Peng Head‐Neck) to verify the expression levels of KRT13, KRT78, and SPRR3 in HNSCC tumor and normal tissues." (PMID 37092360, 2023). "Conversely, KRT13 silencing increased PG expression and nuclear translocation, decreasing EMT, stemness, tumor growth and metastasis." (PMID 35078507, 2022). "KRT13-overexpressing MCF7 cells displayed increased proliferation, invasion, migration and in vivo tumor growth and metastasis to bone and lung." (PMID 35078507, 2022). "Similar to normal prostate stem cells, the cSCs in tumor spheroids exhibited decreased E-cadherin, elevated LC3, an autophagy marker, and KRT13." (PMID 34360875, 2021).
tumor (continued). "We speculate that KRT13 overexpression could disturb cytoskeleton-cell junction desmosome and hemidesmosome protein complex functions, thus affecting cell adhesion and cell architecture and indirectly affecting tumor behavior, neuroendocrine phenotypes, EMT and stemness." (PMID 27835867, 2016). "Some cases demonstrated both KRT13+ HGPIN and tumor foci, however, KRT13 expression was more often observed solely in HGPIN lesions (or benign glands), and while tumor foci were KRT13-." (PMID 27711225, 2016). "In contrast to the relatively low frequency of KRT13+ expression found in the WLA TMA cancer cores, PNBX cores from M1 cases displayed KRT13+ tumor foci in 21/21 cases." (PMID 27711225, 2016). "These levels were lower in tumor than in normal samples for KRT4, KRT13, IL1RN, MAL and TGM3 (Wilcoxon test for paired data, p < 0.001)." (PMID 19835631, 2009). "While OSCC-LM showed no KRT13 and UPK1B expression, some tumor cells of LSCC showed KRT13 and UPK1B expression in 10 of 12 cases (83.3%)." (PMID 38114532, 2023). "Compared to cells in tumor 3 that expressed increased epithelial markers like CDKN2A, CRB3, KRT13, and KRT6, tumor cells in metastatic LN exhibited high expression of mesenchymal markers like CDH3, ECM1, TGFB1, WARS, and VIM, indicating that tumor metastasis was related to EMT." (PMID 36569924, 2022). "Evidence of neoplasia in BE and EAC was characterized by reduced gastrointestinal epithelium markers keratin 13 and keratin 20, relative to RE, while epithelial-to-mesenchymal transition markers vimentin and desmin were increased in BE and EAC respectively, compared to control." (PMID 32650561, 2020). "Tumor features were assessed by the evaluation of spheroid’s growth and proliferative ability in vitro, and the expression of E-Cadherin, a negative marker of the Epithelial to Mesenchymal Transition (EMT), KRT13, and the differentiation marker Keratin 10 (KRT10)." (PMID 37443031, 2023). "The relationship between KRT13 and HGPIN may be important to consider in tumor initiation." (PMID 27711225, 2016). "Tissue staining further revealed that KRT13, PEDF, and HPX are predominantly expressed in basal cells of the benign tissue, whereas they are not detected in tumor areas where basal cells have been lost." (PMID 35267445, 2022). "Interestingly, we observe that non-diseased bladder epithelium exhibits a similar extent of methylation at HOXB2 and KRT13 as the non-invasive disease, while at FRZB the non-diseased tissue has a significantly lower extent of methylation than either of the 2 tumor types." (PMID 20808801, 2010). "In addition to enrichment for keratins found in normal spheroid stem cells (KRT13, 23, 80, 78, and 4), a group of other keratin genes that includes KRT10, 19, 6, 75, 16, 79, 3, and 82 were enriched in the cSCs relative to the non-cSC population of tumor spheroids." (PMID 34360875, 2021).
cancer (36 papers, 2011 to 2025). A tumor composed of atypical neoplastic, often pleomorphic cells that invade other tissues. "It has also been shown that KRT13 is transcriptionally suppressed during TGF-β1-induced EMT, suggesting implication of KRT13 in a hallmark of cancer, i.e., invasion and metastasis." (PMID 36949761, 2023). "KRT81, KRT6A, and KRT13 are examples of these genes that have been linked to cancer metastasis and migration in humans." (PMID 37817112, 2023). "Among the other genes of our signature upregulated in STS samples are C16orf74 and KRT13, which are associated with poor OS in pancreatic and prostate cancers." (PMID 28927421, 2017). "KRT13 was implicated in urothelial and stem cell differentiation, and has a diverse level of expression in cancer." (PMID 27835867, 2016). "It is possible that the aberrant DNA methylation patterns of the KRT13 promoter are a hallmark for certain types of cancer." (PMID 25527207, 2014). "Studies have shown that KRT13 interacts with several proteins for regulating various signaling networks associated with the survival, death, migration, proliferation, invasion, and metastasis of cancer cells." (PMID 37397364, 2023). "Although the role of KRT13 is different in distinct cancers depending on the context 237, 238, research has revealed that the NSUN2-YBX1-KRT13 pathway stimulates CC cell migration and invasion." (PMID 40860147, 2025). "Among them, five genes (FGG, MYH15, STARD4, SYTL4, and TMEM267) were first associated with cancer procession, while the other three (KRT81, KRT6A, and KRT13) have previously been confirmed to be related to cancer metastasis and migration." (PMID 37817112, 2023). "To explore how KRT13 elicits oncogenic signaling in cancer progression and metastasis, we carried out studies to identify intracellular proteins that were interactive to KRT13." (PMID 35078507, 2022). "We first studied the expression patterns of four potential biomarkers (cytokeratin 13, cytokeratin 17, Ki-67 and laminin 5 gamma 2 chain) in an exploratory cohort containing 54 surgical specimens from confirmed oral squamous malignancies." (PMID 35524231, 2022). "KRT13 is a 54-kDa type 1 acidic intermediate filament protein, which plays different roles in distinct cancers depending on the context." (PMID 35280737, 2022). "We further applied immunostaining to early invasive cancer tissues and found that the number of KRT13+ and KRT15+ cells had decreased." (PMID 35608199, 2022). "Although the potential oncogenic function of KRT13 has been reported, the mechanism by which KRT13 is regulated in cancer cells is elusive." (PMID 35280737, 2022). "In both control and cancer organoids, the expression of Hopx and the suprabasal keratinocyte markers Krt13, Krt4, and Krt6a increased with pseudotime while Lgr6-expressing cells were enriched in undifferentiated cells." (PMID 34785704, 2021). "Furthermore, IHC examination of the tissue showed that KRT13 expression indeed almost completely disappears in mucosal epithelial cells in tumor tissue biopsy specimens, and all cancer cells have a KRT17+ phenotype." (PMID 38540309, 2024). "In cancer, diverse clinical relevance and functions of KRT13 have been reported." (PMID 36610719, 2023). "We focused on KRT13 as a candidate gene responsible for radioresistance in pancreatic CSC because an association of some KRT family genes, such as KRT19, with the stemness of normal and cancer cells has been reported." (PMID 36610719, 2023). "In this study, we identified KRT13 as a novel cancer marker and an oncogenic promoter." (PMID 35078507, 2022). "Krt13, a marker for differentiated suprabasal cells in the lingual epithelium, was expressed in cluster 2 in the control organoids but sparsely expressed in the cancer organoids." (PMID 34785704, 2021). "Second, KRT13 was shown to be expressed in megakaryocytes localized at the sites where cancer cells could gain entry into the bone and/or soft tissue compartments (unpublished observation)." (PMID 27835867, 2016).
cancer (continued). "KRT13+ cancer foci were relatively rare, found in only 30/332 (approximately 9%) of cases." (PMID 27711225, 2016). "Several proteins related to cancer development and progression were identified in the list of abundant proteins in FTC, including Ras-related protein Rab-21 (RAB21), Keratin 13 (KRT13), and Serum amyloid A1 (SAA1)." (PMID 40740986, 2025). "Among them, three genes, i.e., KRT6A, KRT13, and KRT81, were related to cancer metastasis and migration." (PMID 37817112, 2023). "In this study, we found that T-C6 highly expressed KRT13 and FABP5 and clustered in the center of the cancer nest." (PMID 37124494, 2023). "In fact, EGFR was part of a cluster of dysregulated genes and enriched gene sets in the FIR20 cells that define the basal breast (cancer) subtype (LAMC2, TRIM29, COL17A and cytokeratin genes (KRT6, KRT7, KRT13, KRT15))." (PMID 35579852, 2022). "Along with common keratins (KRT13/23/80/78/4) in normal stem cells, unique keratins (KRT10/19/6C/16) were enriched in cancer stem-like cells." (PMID 34360875, 2021). "As a control for our analysis, HeLa cancer cell line expressed cytokeratin 5/8, 18 and 19, but not cytokeratin 13, in consistence with the reported results in HeLa cell line." (PMID 27344169, 2016). "Despite enhanced tissue-specific KRT13 protein expression in several cancer types, its potential function in different stages of cancer progression and metastasis has not been elucidated." (PMID 27835867, 2016). "Besides, these genes, ADAMTS2, KRT9, KRT13, LY6D, had been reported in a variety of cancers." (PMID 35237592, 2022). "Interestingly, KRT13+ cancers cells consistently display a luminal profile, with absent P63 expression and strong KRT8 and PSA." (PMID 27711225, 2016).
infection (4 papers, 2019 to 2024). The state of being infected such as from the introduction of a foreign agent such as serum, vaccine, antigenic substance or organism. "Only 2 genes were shared in every comparison when treatment was constant and infection status was compared: those encoding keratin 13 (Krt13) and cytosolic phospholipase A2 gamma (Pla2g4c)." (PMID 34928716, 2022). "SARS-CoV-2 RNA+ host-target cells are highly heterogenous, including developing ciliated, interferon-responsive ciliated, AZGP1high goblet, and KRT13+ “hillock”-like cells, and we identify genes associated with susceptibility, resistance, or infection response." (PMID 34352228, 2021). "Furthermore, proteins related to the cytoskeleton and cytoskeleton remodeling (KRT2 and PLXNA4) and genes coding for components of the cytoskeleton, KRT13 (LOC100515166), KRT17 (LOC100737113), KRT6A, and BFSP1, were significantly higher expressed after infection with swH1N1 compared to huH1N1." (PMID 39247193, 2024).
adenocarcinoma (2 papers, 2022 to 2023). A common cancer characterized by the presence of malignant glandular cells. "We observed basal cell staining for KRT13, PEDF, and HPX in benign regions of the gland, a cell type that is absent in acinar-type adenocarcinomas." (PMID 35267445, 2022).
KRT13 also shares sentences with these, for which no sentence is quoted: dysplasia (4 papers); Oral leukoplakia (3); colorectal cancer (2); genetic disorder (2); leukoplakia (2); vulvar intraepithelial neoplasia (2); Arthritis (1); brain tumors (1); bullous congenital ichthyosiform erythroderma (1); carcinomas in situ (1); chronic periodontitis (1); COVID-19 (1); cyst (1); esophageal tumors (1); gastric cancer (1); gynecological cancers (1); head and neck squamous cell carcinoma (1); hepatocellular carcinoma (1); hyperplastic (1); influenza infection (1); invasive carcinoma (1); keratoconus (1); laryngeal squamous cell carcinoma (1); lichen planus (1); lung adenocarcinoma (1); lung squamous cell carcinoma (1); lymph node metastasis (1); metastatic prostate carcinoma (1); middle ear cholesteatoma (1); mucosal (1).
A further 14 diseases each share a sentence with KRT13 in 1 paper.